ENSG00000278020
Gene: Miscellaneous RNA gene on chromosome 7 (27,188,816 to 27,188,994, forward strand). Ensembl gene ENSG00000278020.
Gene Ontology:
Biological process: negative regulation of gene expression